RNASE10 (ribonuclease A family member 10 (inactive))
Description:
Secreted proximal epididymal protein required for post-testicular sperm maturation and male fertility. May be involved in sperm adhesion to the egg zona pellucida. Does not have ribonuclease activity (By similarity).
Synonyms: RNASE9; RAH1
Tractability: Antibody: UniProt places it where antibodies can reach, with medium confidence; UniProt predicts a signal peptide or a membrane-spanning region; its Gene Ontology location is reachable by antibodies, with medium confidence.
Gene: Protein-coding gene on chromosome 14 (20,505,537 to 20,513,884, forward strand). Ensembl gene ENSG00000182545.
Subcellular location: Secreted
Gene Ontology:
Molecular function: protein binding; RNA nuclease activity; nucleic acid binding
Biological process: defense response to Gram-positive bacterium; heterotypic cell-cell adhesion; positive regulation of cell-cell adhesion; positive regulation of flagellated sperm motility; regulation of fertilization
Cellular component: extracellular region
Genetic constraint (gnomAD): Loss-of-function variants: 4 observed, 2.34 expected, observed/expected ratio (o/e) 1.71, 90% interval 0.69 to 1.94. That is too few expected variants to judge how well the gene tolerates losing a copy. Missense variants: 276 observed, 271.23 expected, observed/expected ratio (o/e) 1.02, 90% interval 0.92 to 1.12. Synonymous variants: 97 observed, 99.59 expected, observed/expected ratio (o/e) 0.97, 90% interval 0.82 to 1.15.
Homologues: Orthologues: macaque RNASE10 (93% identical), guinea pig RNASE10 (73% identical), dog RNASE10 (68% identical), pig RNASE10 (66% identical), rabbit RNASE10 (66% identical), rat Rnase10 (65% identical), mouse Rnase10 (64% identical). Paralogues in human: RNASE1 (19% identical), RNASE11 (19% identical), RNASE4 (19% identical), RNASE12 (18% identical), RNASE6 (18% identical), RNASE7 (18% identical), RNASE8 (16% identical), RNASE3 (15% identical), RNASE2 (14% identical), RNASE9 (14% identical), ANG (13% identical), RNASE13 (12% identical).
Diseases named in the same sentence as RNASE10 in open-access papers:
RNASE10 is named in the same sentence as 2 diseases in open-access papers, as found by Europe PMC text mining. Sharing a sentence is not in itself a finding about the gene and the disease. The quoted sentences say what the papers report.
Aleutian disease (1 paper, 2024). "From this, we identified several candidate genes contributing to the growth and feed efficiency (ARID1B, APPL1, TOX, and GPC5), reproduction (GRM1, RNASE10, WNT3, WNT3A, and WNT9B), pelt quality (MYO10, and LIMS1), and Aleutian disease tests (IFNGR2, APEX1, UBE3A, and STX11)." (PMID 38167844, 2024).
viral infection (1 paper, 2020). "This category contained the nucleases RNASE7, RNASEH2A, RNASE10, and EXO1, as well as proteins regulating nucleases, like the OAS-protein family that are known to activate RNase L activity upon viral infection." (PMID 32545414, 2020).